GNG4 (G protein subunit gamma 4)
Diseases named in the same sentence as GNG4 in open-access papers (continued):
Sharing a sentence is not in itself a finding about the gene and the disease.
Alzheimer disease (1 paper, 2021). A progressive, neurodegenerative disease characterized by loss of function and death of nerve cells in several areas of the brain leading to loss of cognitive function such as memory and language. "Currently, the research concerning the biological functions of GNG4 is still very limited and mainly focused on neurodegenerative diseases such as Alzheimer’s disease." (PMID 34016944, 2021).
Anxiety (1 paper, 2018). Intense feelings of nervousness, tension, or panic often arise in response to interpersonal stresses. "Slc38a3 and Gng4 expression were altered in EFhd2 knockout mouse associated with anxiety and alcohol addiction." (PMID 29391390, 2018).
astrocytomas (1 paper, 2016). "Since GNG4 was found to be down regulated in GBM and not in grade II and grade III astrocytomas, it is evident that GNG4 has important role to play in GBM aggressiveness." (PMID 27382437, 2016).
cervical cancer (1 paper, 2025). A primary or metastatic malignant neoplasm involving the cervix. "GNG4 encodes the G protein γ subunit and shows significant differential expression in our analysis, but its role in cervical cancer remains poorly understood." (PMID 40395456, 2025). "GNG4 displayed the most dramatic increase (3.5-fold), suggesting its potential as a cervical cancer biomarker." (PMID 40395456, 2025). "Based on existing literature, GNG4 may participate in cell signal transduction and migration processes, and its high expression in cervical cancer might promote tumor cell invasive capacity, though the exact mechanism needs to be verified through functional experiments." (PMID 40395456, 2025).
Cirrhosis (1 paper, 2022). A chronic disorder of the liver in which liver tissue becomes scarred and is partially replaced by regenerative nodules and fibrotic tissue resulting in loss of liver function. "In this study, GNG4 was significantly hypermethylated and one of the top 10 significantly down-regulated genes in NAFLD HCC patients with cirrhosis, suggesting that GNG4 may be a potential clinical therapeutic target for NAFLD HCC patients with cirrhosis by inhibiting tumor metastasis." (PMID 36397165, 2022). "Compared to non-NAFLD of HCC patients with cirrhosis, GNG4, EPCAM, SPARCL1, DGKK, and SLC39A4 were down-regulated and HOXD9 was up-regulated in NAFLD of HCC patients with cirrhosis." (PMID 36397165, 2022).
Cognitive impairment (1 paper, 2022). Abnormal cognition is characterized by deficits in thinking, reasoning, or remembering. "Specific variants in GNG4 have been correlated with cognitive impairment." (PMID 33960101, 2022).
liver cancer (1 paper, 2022). An epithelial or non-epithelial malignant neoplasm that arises from the liver. "As liver cancer is considered an immunogenic tumor, the relationship between the expression of DOCK2, SCTR, TANC1, ALKBH7, FREM2, and GNG4 and the levels of immune cells and stromal cells was assessed." (PMID 35620462, 2022).
lymph node metastases (1 paper, 2022). "GNG4 expression was also significantly increased in patients with lymph node metastases and distal metastases." (PMID 35456499, 2022).
melanoma (1 paper, 2022). A malignant, usually aggressive tumor composed of atypical, neoplastic melanocytes. "Additionally, GNG4 can also predict the immunotherapy of melanoma, which may be an indicator of Pan-cancer." (PMID 35456499, 2022). "Interestingly, GNG4 predicted the same prognosis for immunotherapy in a melanoma cohort." (PMID 35456499, 2022).
psoriatic arthritis (1 paper, 2025). Joint inflammation associated with psoriasis. "A separate expansive GWAS listed an additional GNG4 variant that was associated with psoriatic arthritis (PsA)." (PMID 41427421, 2025).
rectal adenocarcinoma (1 paper, 2021). "In rectal adenocarcinoma, four hub genes including CXCL1, CXCL2, CXCL3, and GNG4 were highly expressed at the gene and RNA levels." (PMID 34269159, 2021).
rheumatoid arthritis (1 paper, 2025). A chronic, systemic autoimmune disorder characterized by inflammation in the synovial membranes and articular surfaces. "A recent large, multi-ancestry genome-wide association study (GWAS) found that genetic variation at the GNG4 locus is associated with rheumatoid arthritis (RA) susceptibility." (PMID 41427421, 2025).
thymoma (1 paper, 2022). A neoplasm arising from the epithelial cells of the thymus. "Bisulfite pyrosequencing in 46 TEN and 20 paired thymus tissues revealed higher promoter methylation of G protein subunit gamma 4 (GNG4), growth hormone secretagogue receptor (GHSR), homeobox D9 (HOXD9) and spalt like transcription factor 3 (SALL3) in TC than in thymoma." (PMID 35409405, 2022).
tumor (21 papers, 2011 to 2026). "High levels of GNG4 in primary tumor tissue have been reported to be associated with short overall survival times and the likelihood of liver metastasis recurrence." (PMID 35456499, 2022). "GNG4 has been reported to be associated with tumour immunity." (PMID 36845726, 2023). "High GNG4 expression in OS is associated with tumour progression." (PMID 36845726, 2023). "Moreover, statistical analysis showed that GNG4 expression was also significantly associated with tumor grade and patient’s prognosis, which was similar to PSMC2." (PMID 34016944, 2021). "According to the tumor suppressor role of this protein, in the present study, GNG4 has downregulated, which will lead to tumor growth." (PMID 39552710, 2024). "Pan‐cancer analysis demonstrated higher GNG4 expression in tumours than in paired normal tissue in human cancers." (PMID 37448185, 2023). "We found that these genes are primarily related to different pathological process resulting in the suppression of tumor progression, such as GNG4 and NPY." (PMID 37058060, 2023). "In the TCGA data, our analysis also confirmed that GNG4 was significantly overexpressed in OS and most other tumours." (PMID 36845726, 2023). "GNG4 mRNA levels were highly expressed and positively correlated with various tumour stages, including LUAD, PAAD, COAD, KIRP, BLCA and LIHC, implying its potential carcinogenic effect." (PMID 37448185, 2023). "Pancancer RNA-Seq data were further used to verify the differential analysis of GNG4 expression in 33 human tumours." (PMID 36845726, 2023). "Just as GNG4 was expressed inconsistently in tumours, the relationship between GNG4 and immunomodulators or immunoregulatory cells was diverse." (PMID 37448185, 2023). "Guanine nucleotide binding (G) protein subunit γ 4 (GNG4) is closely related to the malignant progression and poor prognosis of various tumours." (PMID 36845726, 2023). "Significantly, GNG4 expression was found to negatively correlate with tumour‐infiltrating immune cells, ICP, TMB and MSI in CC." (PMID 37448185, 2023). "In general, the high expression of GNG4 was closely related to tumour relapse, metastasis and TNM stage in patients." (PMID 36845726, 2023). "GNG4 plays an important role in promoting tumour cell adhesion, migration, proliferation, and invasion by binding GPCRs." (PMID 36845726, 2023). "The overexpression of CACNA2D1, JUN, GNG4, NGF, MYC, and MAPK4K4, components of the MAPK pathway, is associated with tumor aggressiveness and chemotherapy resistance." (PMID 36344487, 2022). "Overall, we determined that GNG4 is specifically expressed in exhausted CD4+ T cells in BLCA tumor microenvironment." (PMID 35456499, 2022). "Overexpression of GNG4 in GBC tissues and cell lines was observed in this study, which was further significantly associated with more advanced tumor grade and poorer prognosis." (PMID 34016944, 2021). "In the current study, we try to understand the role of GNG4 as a tumor-suppressor in GBM and also elucidate the GPCR signaling which is regulated by it." (PMID 27382437, 2016). "Overexpression of GNG4 was found to inhibit proliferation and colony formation of GBM cell lines and in vitro transformation of immortalized human astrocytes, thus suggesting a potential tumor suppressor role of GNG4 in GBM." (PMID 27382437, 2016). "From this study, it is evident that GNG4 is a tumor suppressor in GBM which functions by abrogating the migration property of GBM cells through inhibition of mainly the ERK pathway downstream to CXCR4/SDF1α signaling axis." (PMID 27382437, 2016). "The importance of GNG4 as a potential tumor suppressor was evaluated by ectopically over expressing the gene in GBM cell lines." (PMID 27382437, 2016). "GNG4, which encodes a Gγ subunit, has been implicated in regulating PI3K/AKT and MAPK pathways and may influence tumor immune regulation and metabolic adaptation." (PMID 41348762, 2025).
tumor (continued). "Evidently, GNG4 plays an essential role in the transmission of downstream signals of GPCRs to downstream pathways which leads to regulation of biological behaviors of normal and tumor cells." (PMID 39552710, 2024). "Immune infiltration analysis suggested that GNG4 may influence the tumour microenvironment by regulating the proportion of memory B cells." (PMID 36845726, 2023). "Likewise, the genes encoding the retinoic acid receptor responder 2 (RARRES2) and G protein subunit gamma 4 (GNG4) are thought to function as tumour suppressors." (PMID 37276213, 2023). "GNG4 expression was positively correlated with TNM stages, suggesting that GNG4 may be involved in tumour metastasis and progression." (PMID 37448185, 2023). "Patients with high GNG4 expression have a higher tumour stage and poorer prognosis." (PMID 37448185, 2023). "Although many studies have suggested that GNG4 may be a biomarker for poor prognosis in a variety of tumours, this study is the first to investigate the correlation between GNG4 expression and prognosis in OS." (PMID 36845726, 2023). "In recent years, accumulated studies have investigated the role of GNG4 in tumours." (PMID 36845726, 2023). "GNG4 was shown to promote tumour progression in CRC16; however, its potential mechanisms remain unclear." (PMID 37448185, 2023). "In summary, the invasion and metastasis of CC was promoted by GNG4 via multiple mechanisms, which may also explain the tumour immune escape." (PMID 37448185, 2023). "Although these studies confirm the importance of high GNG4 expression in the development and progression of some tumours, the clinical significance and biological function of GNG4 in OS remain unclear." (PMID 36845726, 2023). "Meanwhile, GNG4 has been reported to be a tumor suppressor gene in glioblastoma." (PMID 35456499, 2022). "GNG4 expression is significantly upregulated in patients who are sensitive to radiotherapy and chemotherapy, which may be related to tumor cell growth and proliferation." (PMID 34691179, 2021). "Overexpression of GNG4 also significantly inhibits tumor proliferation." (PMID 34691179, 2021). "Recently, studies have found that the differentially expressed gene GNG4 plays an important role in tumor proliferation; however, GNG4 may have different mechanisms of action in different tumors." (PMID 34691179, 2021). "Hence, it is important to know the status of both CXCR4 up regulation and GNG4 down regulation for the inhibitors to act effectively in reducing tumor cell migration and infiltration." (PMID 27382437, 2016). "Here, we provide evidence that GNG4 behaves as a tumor suppressor in GBM scenario." (PMID 27382437, 2016). "ATF-126 and in less extent Maspin cDNA +DOX cells up-regulated the protein gamma-4 subunit/guanine nucleotide-binding protein 4 (GNG4) gene, a brain-specific protein with potential tumor suppressor activity, which, like Maspin, is up-regulated by hypoxia factors." (PMID 21931769, 2011). "In contrast, GNG4 knockdown or pharmacological inhibition of autophagy restores ARSI sensitivity and suppresses tumor growth." (PMID 41605902, 2026). "•The expression of ENG, GNG4 and ECT2 showed a significant difference between normal and tumor samples, have been identified by GEPIA analysis." (PMID 39552710, 2024). "GEPIA analysis identified three genes, ENG, GNG4, and ECT2, whose expression significantly differed between normal and tumor samples." (PMID 39552710, 2024). "Among them, two vital chemokines (CXCL9 and CXCL10), which trigger the recruitment of CD8+ T cells into the tumor microenvironment (TME) in BLCA, were upregulated in the high-GNG4 group." (PMID 35456499, 2022). "GNG4 was ectopically over expressed in GBM cell lines and its tumor suppressor functions were tested." (PMID 27382437, 2016).
tumor (continued). "Although in cell line-based experiments, GNG4 abrogated both phospho-Erk and phospho-Jnk, but it is evident that in tumor scenario ERK pathway has a more pronounced role and hence is modulated to a greater extent by GNG4." (PMID 27382437, 2016). "Expression-based clustering of cells for the patient-1 tumor sample resolved two HGSOC cell clusters, with fusion RAPGEF5::AGMO evident in tumor cells largely clustered separately from cells expressing SMG7::CH507-513H4.1 and GS1-279B7.2::GNG4, potentially reflecting tumor heterogeneity." (PMID 40086881, 2025). "The activity of immune cells in the high GNG4 expression group decreased, including activated CD4+ T cells and CD8+ T cells, macrophages, Th1 cells, NK cells, DCsl and Th17 cells, leading to reduced TME infiltration, which promoted the growth of the tumour." (PMID 37448185, 2023). "Correspondingly, we found that patients with high GNG4 expression were indeed in an immune-inflamed tumor environment, not immune-excluded or an immune-desert tumor environment." (PMID 35456499, 2022). "In conclusion, for the first time, PSMC2 was revealed as a tumor promotor in the development of GBC, which could regulate cell phenotypes of GBC cells through the interaction with GNG4, and maybe a promising therapeutic target in GBC treatment." (PMID 34016944, 2021). "We selected samples where CXCR4 RNA levels are high (Log2 ratio > 2) i.e., tumor cells which might be dependent on CXCR4 signaling, and divided those patients into GNG4 high (RNA Log2 ratio > −0.79) and GNG4 low (RNA Log2 ratio < −0.79) groups." (PMID 27382437, 2016). "Sequencing of the patient-1 tumor sample yielded 497 total cells, with 92 cells (19%) identified as HGSOC cells, from which we identified only four somatic fusion transcripts: SMG7::CH507-513H4.1 (26 cells), RAPGEF5::AGMO (6 cells), NTN1::CDRT15P2 (five cells), and GS1-279B7.2::GNG4 (five cells)." (PMID 40086881, 2025). "Sequencing of the Patient-1 tumor sample yielded 497 total cells, with 92 cells (19%) identified as HGSOC cells, from which we identified only four somatic fusion transcripts: SMG7::CH507–513H4.1 (26 cells), RAPGEF5—AGMO (6 cells), NTN1--CDRT15P2 (5 cells), and GS1–279B7.2--GNG4 (5 cells)." (PMID 38464114, 2024). "Similarly, there was a significant negative correlation between GNG4 expression and TIICs in the tumour microenvironment (TME) that were observed by using the ‘ssGSEA’ algorithm." (PMID 37448185, 2023). "Moreover, our mechanistic study recognized GNG4 as a potential downstream target of PSMC2, knockdown of which could aggravate the tumor suppression induced by PSMC2 knockdown in vitro and in vivo." (PMID 34016944, 2021). "Here we see that mesenchymal subtype of GBM, characterized by highly infiltrative tumor, has very high levels of CXCR4 and very low levels of GNG4 compared to the other subtypes which suggests that CXCR4 pathway might be a primary oncogenic signaling pathway in this type of tumor." (PMID 27382437, 2016). "Moreover, in GBM patients from TCGA data, we observe that phospho-Mek1, and not phospho-Jnk, levels are higher in GNG4 low tumor as compared to those where GNG4 is high, which is corroborated by the fact that chemical inhibitor against ERK pathway abrogates GBM cell migration to the maximum extent." (PMID 27382437, 2016).
cancer (20 papers, 2018 to 2025). A tumor composed of atypical neoplastic, often pleomorphic cells that invade other tissues. "GNG4 encodes a member protein of the G protein family that involved in cancer development and growth." (PMID 34299042, 2021). "Indeed, previous reports of GNG4 expression in cancer-associated T cell subsets as well as agonist-selected PD1+ CD8αα T cells in thymus also indicate an activation-induced mechanism." (PMID 41427421, 2025). "The genes with the most significantly decreased expression in spleens from the Mg2800 diet group included Ano5 (anoctamin 5) and Gng4 (G protein subunit gamma 4), and both are associated with worse cancer outcomes and favor proliferation, migration, and invasion." (PMID 39683640, 2024). "The functional enrichment analysis showed that the expression of GNG4 was related to multiple cancer signalling pathways and immune cell infiltration in OS." (PMID 36845726, 2023). "GNG4 was stably and highly expressed in cancer tissues compared with normal adjacent tissues in the TCGA and GSE39582 data sets." (PMID 37448185, 2023). "Of the 17 cancers with normal matched tissue, GNG4 mRNA expression was upregulated in human cancers such as CHOL, COAD, LIHC, LUAD, LUSC and READ, and downregulated in cancers such as KICH, KIRC, KIRP, STAD, THCA and UCEC." (PMID 37448185, 2023). "Based on RNA sequencing data obtained from the TCGA and GEO databases, the expression pattern and immune characteristics of GNG4 were comprehensively examined using a pan‐cancer analysis." (PMID 37448185, 2023). "In total, the results of our study suggested GNG4’s up-regulation as a novel potential diagnostic biomarker in CRC patients of different races, cancer stages, genders, age groups, and body weights." (PMID 34473751, 2021). "Upregulation of GNG4 in lung, colon, and gastric cancers was positively correlated with cell metastasis and poor prognosis." (PMID 34299042, 2021). "Although its role in Tfh biology has been underappreciated to date, GNG4 expression has appeared in DEG analyses of human T cells, including Tfh, thymic CD8αα T cells, cancer-associated subsets, and was listed after mass spectrometry studies of CD4 T cells stimulated in vitro." (PMID 41427421, 2025). "The GNG4 methylation level was significantly lower in cancer tissues compared with normal tissues." (PMID 37448185, 2023). "In summary, pan‐cancer analysis suggested that GNG4 is an oncogene." (PMID 37448185, 2023). "A pan‐cancer immunological correlation of GNG4 aimed to determine cancer types that may benefit from anti‐GNG4 immunotherapy." (PMID 37448185, 2023). "Pan‐cancer analyses aim to depict the immunological role of GNG4 comprehensively and thus to determine cancer types that may benefit from anti‐GNG4 immunotherapy." (PMID 37448185, 2023). "A pan‐cancer analysis of GNG4 using the Timer database was performed." (PMID 37448185, 2023). "Our research revealed that GNG4 may be involved in the initiation of several key steps in the cancer immune cycle." (PMID 37448185, 2023). "Finally, CC was shown to be an ideal cancer for anti‐GNG4 immunotherapy." (PMID 37448185, 2023). "GNG4 and CCL5 are involved in multiple facets of cancer biology, including cell proliferation, migration, and immune cell recruitment." (PMID 40395456, 2025). "GNG4 was negatively correlated with TMB and MSI in several cancers, with the strongest correlation detected in CC." (PMID 37448185, 2023). "On the other hand, the upregulated genes, such as GNG12, GNG4, WNT9A, EDNRB, FGF18, LAMA3, MMP2, etc., were found in pathways in cancer." (PMID 36239109, 2022). "Present study demonstrated that GNG4 was significantly (p<0.05) overexpressed at mRNA level in CRC patients of different races, cancer stages, genders, age groups, and body weights." (PMID 34473751, 2021).